TF (transferrin)
Diseases named in the same sentence as TF in open-access papers (continued):
Sharing a sentence is not in itself a finding about the gene and the disease.
tumor (continued). "To therapeutically target the CR factors, we used histone deacetylase (HDAC) inhibitors to collapse the chromatin architecture and induce topological blurring of superenhancer loops, abrogating core TF expression and halting tumor growth." (PMID 41392987, 2025). "Both transferrin and lactoferrin conjugated SPIONs surpass many clinical agents and enable the detection of submillimeter tumor foci." (PMID 41583439, 2025). "For instance, PLGA NPs have been shown to enhance the uptake of methotrexate by tumor cells in a transferrin-mediated manner." (PMID 39859159, 2025). "The downregulation of TF expression in Pan-NETs was shown to inhibit tumour cell proliferation in vitro." (PMID 41228199, 2025). "The transferrin protein enhanced the tumor targeting properties and, consequently, the antitumor potency." (PMID 40346933, 2025). "Having established the BBB permeability of Cur-Nio and TF-Cur-Nio, we further evaluated the anti-tumor efficacy of TF-Cur-Nio in vivo." (PMID 40140588, 2025). "Calibrate PBPK–ML frameworks for ginsenoside carriers to simulate EPR vs ligand-mediated targeting, enabling in silico screening of folate, transferrin, or peptide modifications on Rg3 or Rb1 nanoparticles to maximize tumor or brain uptake." (PMID 40709093, 2025). "The TPM-Azo was prepared by covalent functionalization of polylysine (Plys) with the tumor-targeting protein transferrin (TF), the MitP, and PEG to improve biodispersibility and biocompatibility." (PMID 40429669, 2025). "Functionalization with targeting ligands such as folate, RGD (Arginine-Glycine-Aspartic acid) peptides, and transferrin has further enhanced their specificity, allowing for tumor targeting, blood-brain barrier (BBB) penetration, and site-specific therapy." (PMID 41002535, 2025). "Through transferrin modification, Tf-PE-MEs accumulated at the tumor site efficiently with overexpressed transferrin receptor (TfR) on the surface of A549 cells." (PMID 41303330, 2025). "In healthy male mucosa, positive correlations between the ceruloplasmin/transferrin ratio and EMT markers suggest a coordinated regulation, while their loss in tumor tissue implies a disruption during CRC progression." (PMID 40507970, 2025). "Nanoparticles of various architectures—liposomes, dendrimers, polymeric micelles—can be surface-modified (e.g., with monoclonal antibodies, peptides, transferrin) to enhance tumor targeting and reduce off-target distribution." (PMID 40942013, 2025). "Transferrin mediates iron pool, ROS, and lipid peroxidation lowering inside circulating tumor cells and, thus, induces the resistance of these cells to ferroptosis and strengthens their metastasis-inducing potential." (PMID 40227202, 2025). "Further mouse models showed that transferrin was elevated in both the plasma and liver tissue of LM and aggravated tumor LM, whereas LM was attenuated by transferrin knockdown." (PMID 39810853, 2025). "Transferrin (TRF) exploits the overexpression of TRF receptors on rapidly proliferating tumor cells, a strategy validated in clinical trials with TRF-targeted liposomal oxaliplatin." (PMID 41216197, 2025). "Future directions should emphasize rational design of dual-targeting nanocarriers, employing ligands for both BBB penetration (e.g., angiopep-2, transferrin, lactoferrin) and tumor specificity (e.g., RGD peptides, EGFR, folate)." (PMID 41009025, 2025). "Amidst tumor targeting, transferrin has gained significant popularity, particularly in the exploration of its application for brain malignancies, due to its ability to penetrate the BBB via receptor-mediated transport." (PMID 38791253, 2024).
tumor (continued). "The immunohistochemical analysis of the VX2 tumor-bearing rabbit tumor showed that TF-Nanogels exhibited a significant antitumor immune response." (PMID 38951911, 2024). "Similar to ligand-binding integrins, transferrin is also utilized in tumor cell targeting due to its deregulated expression in certain tumor cells." (PMID 38791253, 2024). "We found that plasma membrane fractions from male tumors bound significantly more transferrin per milligram of tissue compared to female tumor samples." (PMID 38287054, 2024). "The prevalence of ID, diagnosed by decreased transferrin saturation below 20%, was 42.6% in tumor patients and 33% of all patients were anemic." (PMID 38240843, 2024). "In comparison, in a previous study, we built a feedforward neural network to predict transcriptomic profiles from TF expression, for which we reported an out-of-sample prediction on tumor data with 80% predicted variance." (PMID 39568475, 2024). "Upon binding to TF, the antibody is internalized into tumor cells, where it is cleaved by lysosomal proteases, releasing MMAE and ultimately inducing cell division inhibition and apoptosis." (PMID 39070179, 2024). "Recent studies have shown that the interaction between TF and VIIa (FVIIa) can impact angiogenesis, cancer stem cell activity, tumor growth, invasion, and metastasis through signal transduction pathways." (PMID 39070179, 2024). "As a result, the tumor microenvironment was remodeled and the antitumor metastasis effect of TF-Nanogels was further improved." (PMID 38951911, 2024). "Transferrin-coated lipid–polymer nanoparticles have been used to deliver afatinib into tumour cells (entry 4)." (PMID 39459317, 2024). "Aside from causing thrombosis in PDAC, high TF expression was long known to correlate with PDAC’s histological grade; in 1999, it was reported that TF can promote PDAC growth and tumor cell invasion in vivo." (PMID 38473827, 2024). "In vivo experimental results also demonstrated that BCHE effectively induced ferroptosis through GPX4 downregulation and Transferrin upregulation in tumor-bearing mice." (PMID 38906931, 2024). "The intravenous administration of transferrin-loaded lipid–polymer hybrid nanoparticles loaded with PLB resulted in the disappearance of 40% of B16-F10 tumours and the regression of 10% of tumours." (PMID 39275349, 2024). "This also includes expression within the neo-vasculature of the tumour, overall making TF a potentially useful TAA to target in tumour immunotherapy." (PMID 39105809, 2024). "Knocking down endogenous transferrin impairs tumor formation by melanoma circulating tumor cells; however, this defect in tumorigenesis can be partially offset by lipophilic antioxidants such as ferrostatin-1 and vitamin E." (PMID 38921444, 2024). "TF, thrombin, and PAR‐1 have each been linked to PDAC tumor progression, and fibrin(ogen) has been implicated in supporting tumor growth and metastasis of multiple epithelial cell‐derived malignancies." (PMID 37971174, 2024). "This study has further emphasised the immunotherapeutic potential of targeting TF expressed by tumour cells." (PMID 39105809, 2024). "Analysis from the GEPIA2 database revealed aberrant expression of these three hub TF genes in various tumor samples." (PMID 39045407, 2024). "The utilisation of dual recognition immunotherapies, e.g. BiTEs have the potential to not only improve the safety profile of TF-targeted cancer therapies by only activating T cells in the tumour vicinity." (PMID 39105809, 2024). "Doxorubicin-encapsulated liposomes were effectively targeted to both TF-expressing tumour cells via the use of anti-TF Fab fragments PEG-conjugated to liposomes." (PMID 39105809, 2024).
tumor (continued). "This study signifies the use of transferrin for effective targeting of the BBB as well as the role of dual payloads in achieving more potent tumor cell death." (PMID 39457052, 2024). "Earlier findings from other groups that the depletion of flTF can reduce tumor growth and thrombosis in murine models led to the exploration of targeting “total TF” in human clinical trials." (PMID 38473827, 2024). "Transferrin < 200 mg/dL correlated with more frequent tumor dissemination at level 2 and 3 (p-values: 0.001 and <0.001, respectively)." (PMID 38339372, 2024). "In line with their higher CD71 expression, tumor-infiltrating OX40+ Tregs displayed a stronger capacity to internalize a fluorescently labeled transferrin ex vivo." (PMID 38954474, 2024). "Iron transporting proteins in cells such as transferrin composed of plasma proteins which absorbs iron from systemic circulation is studied for tumour targeting." (PMID 37552393, 2024). "TalaA promotes ferroptosis by increasing intracellular reactive oxygen species and up-regulating transferrin and heme oxygenase 1, thereby inhibiting tumor cell proliferation, DNA replication and colony formation." (PMID 39544949, 2024). "In tumors, 67Ga-citrate administered into the veins binds to transferrin in the serum to form a transferrin-67Ga complex, which acts on the transferrin receptor of the tumor cells and is taken up into the cells." (PMID 39009630, 2024). "There was a higher concentration of afatinib present in tumour tissue when delivered by transferrin-coated nanoparticles than both free drug and drug-loaded nanoparticles without transferrin." (PMID 39459317, 2024). "While this reduces the interaction between CAR T cells and non-malignant cells expressing TF, in turn decreasing on-target off-tumour effects, there are still reports of low level TF expression within the body." (PMID 39105809, 2024). "A primary requirement for TF-targeting strategies will be enforcing conditional activity of such agents specifically at the tumour site." (PMID 39105809, 2024). "Real-time fluorescence imaging indicated a significant accumulation of DiR-labeled TF-TP@LIPs at tumor sites in nude mice, in contrast to DiR-only or DiR-labeled, indicating that modification with transferrin enhanced drug targeting to the tumor tissues." (PMID 37893242, 2023). "The observed high phototoxicity reported for HT-29 cancer cells (95–98%) was explained by the specific binding of the lectin to the TF antigen, expressed onto the tumor cell membrane." (PMID 38139227, 2023). "TAT-PEG-SN38, after targeted modification by Transferrin (Tf), can significantly increase the toxicity of liposomes and enhance the killing capacity of tumor cells." (PMID 36678807, 2023). "Coupling adriamycin to TF takes advantage of TF's recognition of TfR1 to allow for precise delivery of adriamycin to cancer cells for targeted tumour therapy." (PMID 36897430, 2023). "TF promotes tumor-directed angiogenesis by upregulating vascular VEGF expression and downregulating the angiogenesis inhibitor (thrombospondin) expression." (PMID 37046617, 2023). "UCNP@GA-FeIII probes acquire specific tumor-targeting ability by absorbing the unsaturated transferrin from serum that recognizes the overexpressed TfR1 on the surface of various solid, malignant tumor cells, including colorectal cancer cells LS180." (PMID 36677534, 2023). "Human nanoplatelets were engineered in vitro with molecular functionalities for tumor targeting, imaging and therapy by loading them with cytotoxins and vital stains and by attaching transferrin to their outer membrane." (PMID 36836127, 2023). "Images of red-conjugate transferrin uptake for tumor cells in each mixed system were captured on Laser Scanning Confocal Microscopy (Zeiss) with a Z stack mode and then 3D reconstruction of TF co-localization with the tumour cell were performed." (PMID 37143164, 2023).
tumor (continued). "A means to detect or to image tumor-bound nanoplatelets in vivo was realized by coupling Cy7-transferrin to their outer surface using the same method." (PMID 36836127, 2023). "Coagulation factors involved in tumor angiogenesis include TF, FVII, thrombin, thrombin receptor (protease-activated receptor), fibrin, and FXIII." (PMID 37046617, 2023). "It inhibits neutrophil elastase activity and tumor metastasis, and α-AT can prevent TF from binding to TfR1." (PMID 36910614, 2023). "For example, formulations modified with tumor-targeting molecules such as folate and transferrin can be easily recognized and internalized by tumor cells due to their overexpression of folate or transferrin receptors." (PMID 37375753, 2023). "Upon residence in tumor via transferrin (TRF), the BaSO4@ZIF-8/TRF NMΦ can release Zn2+ as an “artificial cytokine” to reverse tumor immunosuppression and induce tumor anoikis." (PMID 37737506, 2023). "Transferrin-lipoplexes containing the therapeutic gene IL12 inhibited tumor growth in CT26-derived tumor-bearing animals, resulting in complete tumor regression in 75% of the treated mice." (PMID 36910614, 2023). "The results of in vivo experiments further showed that TF-TP@LIP had stronger anti-tumor effects in vivo compared with the free TP TP@LIP groups, and the results of in vivo and in vitro studies were consistent." (PMID 37893242, 2023). "This shows that 64Cu-NOTA-FVIIai is very suitable for PET imaging of tumor TF expression, and the TF expression level of different pancreatic tumor models can be distinguished with the use of PET/MRI." (PMID 37188192, 2023). "There are a variety of specific receptors on the surface of tumor cells (such as antibodies, peptides, transferrin, folic acid, etc.)." (PMID 37919282, 2023). "In the Bo1 metastatic model, in vivo and ex vivo imaging showed that short-term DFO treatment improved uptake of fluorescently-labeled transferrin at tumor sites." (PMID 38117806, 2023). "While TF shows tumour-enhancing characteristics, its natural inhibitors, TFPI1 and TFPI2, are associated with tumour-suppressing properties." (PMID 37569483, 2023). "Previous studies have reported that binding of galectin-3 to TF on the transmembrane mucin protein MUC1 of tumour cells induces tumour cell-cell homotypic aggregation that promotes circulating tumour cell resistance to anoikis in hematogenous dissemination." (PMID 37612278, 2023). "Functionally, FOXO3 is a TF that regulates multiple pathways including tumor angiogenesis, and PI3K-AKT signaling pathway." (PMID 36720864, 2023). "We compared in vivo MRI values of tumor tissue to its transferrin/ferritin ratio which serves as a proxy for iron homeostasis." (PMID 37699931, 2023). "Tumor-targeted imaging functionalities were engineered on the nanoplatelets by surface-coupling transferrin, Cy5 and Cy7." (PMID 36836127, 2023). "The findings indicated that modification by transferrin significantly enhanced the tumor-targeting ability of the liposomes and improved their anti-tumor effects in vivo." (PMID 37893242, 2023). "The nanoplatelets were equipped with a novel tumor-targeting function by bioconjugating transferrin (Cy5-transferrin)." (PMID 36836127, 2023). "Based on the transcriptome analysis, Se-PC PDT treatment inhibits angiogenesis, regulates inflammation by the HIF-1, NF-κB and TGF-β signaling pathways and dilutes tumor metabolism by reducing the synthesis of glucose transporters and transferrin." (PMID 37994159, 2023). "Nonetheless, it is essential to note that both the transferrin-bearing and control nanoparticles maintained sizes that remained beneath the threshold necessary for extravasation through the tumor tissue vessels (approximately 400 nm for solid tumors)." (PMID 38004621, 2023).
tumor (continued). "Consistent with our in vitro discoveries, tumours formed in the C1galt1f/f/Erb mice were seen to express higher amounts of TF (12.8 ± 4.8% staining) and low levels of Tn (<1% staining) structures than those in ME C1galt1-/-/Erb mice." (PMID 37612278, 2023). "Galectin-3 binds TF-antigen and this interaction induces diverse pathological processes such as tumor cell aggregation, cancer metastasis, and T cell apoptosis." (PMID 36873388, 2023). "As a result, transferrin conjugation with drug nanocarriers enhances their selectivity to tumor cells, leading to greater efficacy in drug-resistant cells." (PMID 37953758, 2023). "It is known that the presence of a self-navigating molecule (e.g., folic acid, transferrin) favors the targeted delivery of drugs to tumor tissue through mediated endocytosis." (PMID 36678830, 2023). "Various functional ligands, including transferrin, folic acid, polypeptide and hyaluronic acid, have been widely explored to develop tumor-selective drug delivery systems." (PMID 37465582, 2023). "Lastly, nine Hub TF genes were identified by Venn diagramming, which indicated that they played an essential role in the regulation of tumor development." (PMID 37686305, 2023). "FOXO1 is a well-known tumor suppressor, but recent studies also reported tumor-promoting functions of the TF for different tumor entities." (PMID 36817488, 2023). "This pro-tumor SEPEP is also a fully discriminative SEPEP associated with NP_001054.2, the longest isoform of the transferrin gene." (PMID 37726316, 2023). "Previous studies reported that transferrin overexpression in the primary tumor at diagnosis predicted decreased response to drugs, and actively promote the development of metastases." (PMID 38117806, 2023). "Next, GNMs come into contact with the surface of cancer cells, either passively or by active targeting; for example, when coupled to ligands for folate, transferrin, or epidermal growth factor receptors overexpressed on tumor cells, or by magnetic targeting." (PMID 37514033, 2023). "In particular, the authors noticed that salivary transferrin levels were strongly correlated with tumor size, demonstrating its predictive power." (PMID 37623833, 2023). "Transferrin-based nanotherapeutic probes have also been developed to achieve early tumor diagnosis through active targeting." (PMID 37122851, 2023). "As the “noise” depends on uptake from the surrounding tissue, organs with physiologically high uptake of transferrin (e.g. the liver) will have higher noise than tissues with different functions (e.g. non-tumor fat pads)." (PMID 38117806, 2023). "In particular, we introduced novel tumor-targeting and in vivo imaging functionalities in human platelets by surface-coupling transferrin and internal-loading or surface-coupling of near-infrared fluorescence (NIRF) probes, respectively." (PMID 36836127, 2023). "Compared with untargeted liposomes, cisplatin-encapsulated transferrin-conjugated PEGylated liposomes not only increase accumulation in free tumor cells in ascites, but also in solid tumor tissues of the greater omentum." (PMID 36768966, 2023). "Tumor uptake was significantly different with variable TF expression levels and was consistent with TF levels assessed via immunohistochemical staining." (PMID 37188192, 2023). "Ideally, these receptors/transporters are both highly expressed on the CNS endothelial cells and on the tumor itself, as is the case for transferrin and GLUT1, respectively." (PMID 37513992, 2023). "The analysis yielded 258 significant correlations of lncRNAs-TF pairs in tumor samples (n = 2 very strong; n = 11 strong; n = 41 moderate; n = 204 weak)." (PMID 35565409, 2022). "Patients with CRC presenting elevated serum transferrin saturation exhibited preferential iron deposition in macrophages in the tumor microenvironment." (PMID 36136589, 2022).